CSF1 (colony stimulating factor 1)
Diseases named in the same sentence as CSF1 in open-access papers (continued):
Sharing a sentence is not in itself a finding about the gene and the disease.
tumor (continued). "TGCT is predominantly caused by a genetic translocation in the stromal cells of the synovial membrane, resulting in the overexpression of colony stimulating factor 1 (CSF-1) that then recruits CSF1R-expressing cells to the tumor mass." (PMID 36980578, 2023). "The results of EdU staining assays showed that si-SPP1 and si-CSF1 decreased tumor cell proliferation." (PMID 37097499, 2023). "Instead of CSF1 gene rearrangement, we detected increased CSF1 (3'end) copy number with deletion of the 5′ end, coupled with increased expression of CSF1 in tumor cells on RNA scope." (PMID 37305870, 2023). "Macrophages are recruited in tumor sites by various chemokines such as CSF-1, CCL2, 5, CXCL8, and 12, which are secreted from TME." (PMID 38017494, 2023). "The hybrid ABM developed in this paper builds on existing differential equation models and ABMs that focus on specific tumour-macrophage interactions, such as the CSF-1/EGF paracrine loop that mediates cross-talk between tumour cells and macrophages." (PMID 36972297, 2023). "For example, colony-stimulating factor 1 (CSF1) secreted by tumor cells favors the recruitment of monocyte-derived macrophages to the TME and polarizes them to the M2-like manner." (PMID 36941614, 2023). "To assess the role of tumor-derived CSF1 in these model systems, we generated and characterized CSF1 CRISPR-Cas9 knockouts." (PMID 37505292, 2023). "Another study showed that emodin inhibited the secretion of MCP-1 and CSF-1 by tumor cells, thereby reducing macrophage migration to and adhesion to tumor cells." (PMID 37560476, 2023). "Under the effects of tumor-secreted colony-stimulating factor 1 (CSF-1, or M-CSF), TAMs polarize to M2-like, allowing immunosuppressive M2-like TAMs to predominate in tumors." (PMID 37993941, 2023). "Macrophages are relocated to tumor areas and differentiate into TAMs in response to various cytokines, such as IL-34, CSF1, members of VEGFs, and chemokines, such as CCL5 and CCL2." (PMID 37958467, 2023). "The recruitment of TAMs to tumor sites is mediated by tumor-derived effector proteins such as CSF-1, VEGF and chemokines." (PMID 37637050, 2023). "The CSF-1/CSF-1R signaling pathway is also a primary target for inhibiting MDSC recruitment to tumor sites to constrain tumor progression." (PMID 37415162, 2023). "In tumor tissues, the presence of M-CSF, also known as CSF1, promotes carcinoma growth and angiogenesis by a paracrine effect on the CSF1R." (PMID 37663266, 2023). "The expression levels of monocyte chemokines (csf-1 and ccl-2) in tumor cells of mice treated with EGCG were lower, and the cytokine was skewed from M2-to M1, which was manifested as the decrease of IL-6 and TGF-β, and the increase of TNF-α." (PMID 37560476, 2023). "Animals bearing CSF1−/− tumors also showed decreased levels of serum CSF1 as compared to the parental 4T1 tumors, suggesting tumor cells are a significant source of CSF1 present in tumor-bearing animals." (PMID 37505292, 2023). "Colony-stimulating factor-1 (CSF-1) is a well-established tumor stimulator due to its ability to entice and direct the migration of mononuclear cells to tumor locations." (PMID 37138860, 2023). "Yu’s group developed an intelligent nanodrug PFH@LSLP that can target CXCR4, which is highly expressed under tumor hypoxic conditions, and deliver both sorafenib and CSF1/CSF1R inhibitor PLX3397." (PMID 36903458, 2023). "CSFR1 is expressed on the cell surface of monocytes and macrophages, whereas CSF1 (also known as M-CSF) is secreted by tumor cells to recruit and polarize monocytes into TAMs." (PMID 37108657, 2023). "In future studies, it will be important to further explore the mechanisms by which the combination therapy of CSF1 inhibition with vaccine drives tumor suppression within the tumor microenvironment, including the precise contribution of DC subsets." (PMID 37505292, 2023).
tumor (continued). "On the other hand, CSF1, TGF-β, interleukins: 4, 6, 13, 10, and prostaglandin E2 (PGE2), released by tumor cells, can cause macrophage polarization into M2 macrophages." (PMID 37958467, 2023). "This specific tumor type is well-suited for targeting by CSF-1/CSF-1R pathway blockade; and treatment with anti-CSF-1R antibodies has shown significant reduction of CSF-1R+ TAMs within tumor tissues." (PMID 37114134, 2023). "While tumor infiltrating monocytes exhibited higher CSF1/M-CSF activity compared to peritumoral monocytes, they had lower TRAIL/TNFSF10 expression." (PMID 37404757, 2023). "CSF‐1, also known as macrophage colony‐stimulating factor, which stimulates tumor growth in tissues and induces angiogenesis, was significantly upregulated in M2 macrophages." (PMID 37013458, 2023). "It has been found that tumor cells express significant amounts of colony-stimulating factor 1, C-C pattern ligand 2 (CCL2), and monocyte chemotactic protein-1, something which contributes to TAMs’ function in tumor development." (PMID 37513975, 2023). "Our findings thus add to the therapeutic potential of CSF1 targeting agents by employing combinations with vaccines to modulate anti-neoepitope responses in the tumor microenvironment." (PMID 37505292, 2023). "On the one hand, TAMs can promote tumor replication and invasion through colony-stimulating factor 1 and epidermal growth factor, on the other hand, they can express immunosuppressive factors like interleukin to facilitate the immune escape of tumor cells." (PMID 38264667, 2023). "Inhibitors blocking the interaction between CSF1/CSF1R reverses the immunosuppressive tumor microenvironment." (PMID 37092846, 2023). "As an immune-related gene, CSF1 is also involved in the tumor immune microenvironment and stimulates the growth and survival of myeloid-derived suppressor cells and other myeloid-lineage cells." (PMID 37097499, 2023). "In vitro, CSF1 is upregulated 48 h after 3 Gy RT treatment and its blocking results in lower recruitment of TIMs and delayed tumor regrowth after RT in vivo." (PMID 37173782, 2023). "The MoDCs—derived in situ from tumor-infiltrating monocytes recruited by CSF-1 and CCL2—lack CCR7 expression and their anti-tumor activity would mostly entail an in situ activation of T-cell cytotoxicity in tumors." (PMID 37190135, 2023). "Overall, we demonstrated that CSF1/CSF1R signaling inhibition promotes an immune-permissive tumor microenvironment and enhances neoepitope spreading, resulting in enhanced tumor control." (PMID 37505292, 2023). "CSF1/3 are tumor immune‐remodeling genes that varied in the opposite direction, indicating a complicated regulatory circuit of inflammatory cytokines." (PMID 37078828, 2023). "Similar tumor growth curves to the parental cell line were obtained only when implanting 20 times more CSF1−/− cells as compared to the parental cell line." (PMID 37505292, 2023). "Circular RNA (circRNA) CircASAP1 competes with tumor suppressor miRNAs (miR-326 and miR-532-5p) that target CSF1, also promoting the expression of CSF1." (PMID 37663266, 2023). "Overall, the tumor microenvironment recruits TAMs to the tumor stroma and blood vessel edges through hypoxia and the release of the growth factor CSF1 or chemotactic factors." (PMID 35847885, 2022). "They considered the density of macrophages, tumor cells, CSF-1, and (EGF) as the main four variables." (PMID 36439180, 2022). "CSF1 is abundantly expressed by several tumor types; this ligand-receptor pathway has been extensively investigated in tumor models and constitutes a paradigm of TAM-cancer cell interaction." (PMID 35327359, 2022). "In TME, CSF-1 is one of the main growth factors released by tumor cells and stroma cells able to modulate macrophage physiology." (PMID 36359228, 2022).
tumor (continued). "In TSGCTs, the tumor cells have CSF1 rearrangement and it induces CSF1 overexpression, which leads to the mobilization of many inflammatory cells and osteoclast-like giant cells into the tumor tissue." (PMID 36320082, 2022). "CSF1 is a tumor‐promoting cytokine, with the participation of tumor cells, it binds to CSF1R of macrophages, attracts macrophages to the tumor area, and further accelerates the production of TAMs." (PMID 35593325, 2022). "CSF1 [colony stimulating factor 1 (macrophage)] is considered a typical cytokine to promote tumor development." (PMID 35593325, 2022). "Overall, it is possible that aging leads to an increased potential for monocyte to macrophage differentiation, through CSF-1R signaling/increased CSF-1 utilization, that is mediated by both the aging and tumor microenvironment." (PMID 35821822, 2022). "In contrast, the M2 phenotype is generally supposed to participate in immunosuppression and tumor promotion, which is formed after being exposed to macrophage colony-stimulating factor 1 (CSF-1), interleukin 4 (IL-4), IL-10, and IL-13." (PMID 36013403, 2022). "Inhibition of the CSF-1 pathway can be overcome by IL-4 stimulation of TAMs within the tumour microenvironment." (PMID 35359423, 2022). "Accordingly, abundant tumor infiltration by TAMs as well as elevated circulating levels of TAM-relevant cytokines including CCL2, CCL8 and colony stimulating factor 1 (CSF1) have been linked with poor disease outcome in multiple cohorts of cancer patients." (PMID 36319998, 2022). "This analysis does not distinguish between tumor-derived and stromal-derived CSF-1, and the role of the endogenous tumor-derived CSF-1 requires further investigation." (PMID 35292516, 2022). "In GCT cells, miR‐125b expression in tumor cells promoted a microenvironment enriched with TAM via increasing the production of tumor‐derived chemokines CSF1 and CX3CL1 for TAM recruitment." (PMID 35811571, 2022). "Among them, CSF1 plays a special role in differentiation towards tumor-promoting “M2-like” phenotype, and regulation of macrophage motility." (PMID 36077705, 2022). "In several tumor types and murine models, radiation has been demonstrated to induce CSF-1 production which can facilitate macrophage recruitment." (PMID 36249052, 2022). "In the TME, tumor cells secrete CSF-1, which bind to the macrophage CSF-1R receptors to promote their transformation into TAMs." (PMID 36105288, 2022). "Especially, CSF-1 stimulates polarization of neighboring macrophages towards an M2-like phenotype that reciprocally releases CXCL12 to sustain tumor survival via CXCR4." (PMID 36117852, 2022). "Tumor-derived factors such as GM-CSF, CSF-1, and G-CSF signal through signal transducer and activator of transcription 3 (STAT3), CCAAT/enhancer-binding protein β (C/EBPβ) and IRF8 to promote myelopoiesis." (PMID 36031601, 2022). "Mechanistically, an early response to trametinib treatment sensitized tumors to αPD-1-supplementation by attenuating the expression of tumor-derived CSF-1, which reduced the abundance of two CSF-1R+CD11c+ MDSC populations in the TME." (PMID 35292516, 2022). "Recruitment of TAMs to tumor sites is mediated by tumor-derived effector proteins such as CSF-1, VEGF, and chemokines." (PMID 36142818, 2022). "Studies have proved that M2 TAMs tend to promote directional migration in tumor cells' vessels and invasion by the paracrine loop of tumor-derived CSF-1 and TAM-derived EGF/EGF-like ligands, secrete osteonectin, Cathepsin, and TGF-Beta." (PMID 35434132, 2022). "Best responders were those patients with tenosynovial giant cell tumor (TGCTs), a rare tumor type with a central role for CSF-1 in its pathogenesis." (PMID 35053602, 2022). "Studies have shown that miR-148b serves as a tumor-suppressor by blocking CSF1 expression, subsequently inhibiting the TAM infiltration in hepatocellular carcinoma." (PMID 36248881, 2022).
tumor (continued). "Combined with the overall changes to CSF-1R expression it is possible there is increased utilization of CSF-1 in elderly tumor-bearing mice." (PMID 35821822, 2022). "The colony-stimulating factor-1 (CSF-1) produced by tumor cells binds to CSF-1R on the surface of macrophages, thus promoting macrophage proliferation, migration, and polarization to the M2-like phenotype." (PMID 35965509, 2022). "In an aggressive TNBC mouse model, treatment with PARPi + SREBP1 inhibitor + CSF-1 inhibitor significantly improved tumor growth inhibition compared to CSF-1 inhibitor + olaparib." (PMID 36091750, 2022). "In the present study, cases positive for CSF1 on IHC showed CSF1 split signals in greater than 2% of tumor cells." (PMID 36320082, 2022). "Using 4NQO-LCSF-1 and 4NQO-LGFP tumors we provided further evidence to support the influence of tumor-derived CSF-1 on CSF-1R+CD11c+ MDSCs and CD8+ T cells in response to therapy in vivo." (PMID 35292516, 2022). "TAMs are stimulated by CSF-1 to produce epidermal growth factor (EGF) to strengthen tumor invasion and metastasis." (PMID 35672862, 2022). "Tumor cells can secrete CSF-1, which binds to the CSF-1R receptor on the surface of TAMs to promote their polarization to M2 TAMs." (PMID 36105288, 2022). "Myeloid-cells tumor homing is largely regulated by multiple ligand-receptor interactions, mainly the colony-stimulating factor-1 (CSF1R), the C-X-C Motif Chemokine Receptor 2 (CXCR2), the C-C chemokine receptor type 2 (CCR2) and type 5 (CCR5)." (PMID 36077813, 2022). "The release of cytokines and tumor metabolites in the TME: Colony stimulating factor 1 (CSF-1) recruits tumor infiltrating myeloid cells (TIMs) that inhibit tumor immunity, including M2-like TAMs and MDSCs." (PMID 35198442, 2022). "Our previously published study showed that Kindlin-2 in tumor cells was involved in the regulation of the CSF1/EGF oncogenic loop, downstream of TGF-β, to activate growth and metastasis of TNBC tumors in mice." (PMID 35158908, 2022). "The Q-PCR results from all the tumors of each treatment group showed that several chemokines and cytokines were positively correlated with tumor size, including IL-4a, IL-6, IL-10, CSF-1, CSF-2, INF-r, and NOS-2." (PMID 35058524, 2022). "Mitigating KD-induced changes in macrophage polarization through CSF-1 inhibition potentiates anti-tumor activity." (PMID 36428642, 2022). "Regarding PC, androgen blockade therapy and radiotherapy were found to increase myeloid derived suppressor cell (MDSCs) systemically and CSF-1 expression by tumor cells." (PMID 35053602, 2022). "Following irradiation of tumors the DNA damage-induced kinase ABL1 (c-Abl) is recruited into the nuclei of tumor cells to enhance CSF1 transcription." (PMID 36249052, 2022). "Sema4C with plexin-B2 receptor promotes macrophage infiltration in TME, and promotes tumor growth and progression by activating the NF-κB pathway to induce CSF-1 production in breast cancer." (PMID 35155237, 2022). "CSF-1 affects macrophages and monocytes through increased phagocytic, chemotactic activity and tumor cytotoxicity or other ways to affect macrophages and monocytes." (PMID 36131942, 2022). "The EGF family ligands secreted by macrophages and CSF-1 secreted by tumor cells form a paracrine loop between macrophages and tumor cells." (PMID 36510315, 2022). "CSF-1-secreting tumor cells and EGF-secreting TAMs stimulate each other, leading to the migration of both cell types together towards blood vessels." (PMID 36077705, 2022). "The fusion gene induces overexpression of CSF1 mRNA and CSF1 protein (also called macrophage colony stimulation factor) in the tumor." (PMID 36320082, 2022). "TAb2 tumor cells drastically expanded F4/80+ TAMs from bone marrow precursors, requiring CSF1 and VEGF." (PMID 35366939, 2022). "Overall, 50 of 65 TSGCT cases, including 35 of the 44 LTSGCTs and 15 of the 20 DTSGCTs, showed distinct scattered expression of CSF1 in the majority of mononuclear tumor cells." (PMID 36320082, 2022).
tumor (continued). "Multiple studies have demonstrated that CSF-1/CSF-1R is highly expressed in several tumor tissues such as breast cancer, prostate cancer, head and neck cancer, ovarian cancer, gastrointestinal cancer, colon cancer, pancreatic cancer, and mesothelioma." (PMID 36359228, 2022). "CSF-1 is highly expressed in solid tumours and promotes monocyte differentiation into tumour associated macrophages (TAMS) which enhance tumour growth and metastases." (PMID 35350751, 2022). "The immune cells that reside in the tumor microenvironment include lymphocytes, macrophages and polymorphonucleocytes, many of which migrate into the tumor via chemoattractants such as CSF-1, IL-3 and VEGF, and chemokines such as CCL-2." (PMID 35267430, 2022). "The reduction in the accumulation of the MDSCs expressing CSF-1R+CD11c+ seems to be mediated, at least in part, by a reduction in tumor-derived CSF-1." (PMID 35292516, 2022). "FISH revealed CSF1 split signals in 0%, 4%, 6%, 6%, 10%, 10%, and 26% of tumor cells in 7 TSGCTs (4 LTSGCTs and 3 DTSGCTs) that were positive for CSF1 on IHC." (PMID 36320082, 2022). "Colony-stimulating factor 1 (CSF-1) is a cytokine mainly produced by tumor cells that recruits macrophages under pathological conditions." (PMID 35000616, 2022). "Genetic ablation of CSF-1 reduced TAMs infiltration and delayed tumor progression in mouse mammary tumor models." (PMID 36031601, 2022). "Phosphorylation of colony-stimulating factor 1 (CSF-1) promotes the proliferation and transformation of macrophages into TAMs, and tumor cell invasion and metastasis." (PMID 35651605, 2022). "In vitro, PLX3397 inhibited colony-stimulating factor-1 or tumor-conditioned media stimulation of pERK1/2 and reduced the pro-tumor M2 polarization of TAMs." (PMID 35720360, 2022). "TAMs are plastic cells and can be polarized by colony-stimulating factor-1 released by tumor cells into an immunosuppressive M2-like phenotype, producing cytokines, chemokines, enzymes, and exosomes having miRNA, by promoting tumor metastasis." (PMID 36139508, 2022). "CSF-1/CSF-1R signaling is a key activator of the mononuclear phagocyte system, and blockade of CSF-1/CSF-1R creates an environment of reduced immunosuppression and enhanced interferon response that can impede tumor growth." (PMID 35874717, 2022). "Patient-derived datasets confirmed that this enhancer is most active in TNBC individuals, and we were able to detect CSF1 eRNA and mRNA transcripts in patient tumor samples." (PMID 35406623, 2022). "This decrease in stromal CAVIN1 contributes to the upregulation of inflammatory signatures, like increased matrix metalloproteinase-3 (MMP3), dickkopf-1 (DKK1), and CSF-1 secretion, thus attracting macrophages for a tumor-supportive microenvironment." (PMID 36117852, 2022). "The tumor-cell–macrophage paired chemotaxis is driven by a paracrine loop between tumor-cell-secreted colony-stimulating factor 1 (CSF-1) and macrophage-secreted epidermal growth factor (EGF)." (PMID 35565297, 2022). "Macrophages are a heterogenous population of terminally differentiated monocytes that range in their function from pro-inflammatory and anti-tumor (M1 phenotype) to pro-tumor tissue remodeling (M2 phenotype), induced by IL-4, IL-10, IL-13, and CSF-1." (PMID 36223740, 2022). "These malignant behaviors for tumor angiogenesis are mainly influenced by colony-stimulating factor-1, implying the possibility of colony-stimulating factor-1 as a drug target." (PMID 35740577, 2022). "Other studies indicated that colony stimulating factor 1 (CSF-1) is overexpressed in solid tumors to recruit blood cells to suppress tumor immunity with changing their microenvironment." (PMID 36359210, 2022). "In this study, we found that Bag3 and LITAF are key contributors to tumor macrophage infiltration which is mediated by the CSF1 pathway." (PMID 36077705, 2022).